ALB (albumin)
Diseases named in the same sentence as ALB in open-access papers (continued):
Sharing a sentence is not in itself a finding about the gene and the disease.
cancer (continued). "In addition, inflammatory cytokines released from cancer cells and platelets inhibit albumin synthesis in hepatocytes." (PMID 35086516, 2022). "The albumin level in the body obviously affected the survival time of cancer patient." (PMID 35481993, 2022). "It is probable that the characteristics of the cancer (type, aggressiveness) or treatment response to each cancer may be stronger factors affecting patient outcome than serum albumin." (PMID 35672868, 2022). "Multivariate analysis showed that chronic kidney dysfunction, malignant tumor, abnormal neutrophil count, abnormal lymphocyte count, decreased serum albumin level, and increased HbA1c level at admission was independently associated with progression to severe CAP in diabetic patients." (PMID 36344933, 2022). "TMEM206 disruption increased albumin-dependent survival of cancer cells." (PMID 35590106, 2022). "As a result, whether preoperative BMI or serum albumin considered as long-term prognostic factors for OS in individuals receiving PD for cancer remains unclear." (PMID 35773692, 2022). "Therefore, increase of ALB in 2.0 mg/mL of QFG would be benefit to the cancer patients with surgery." (PMID 35280511, 2022). "In other words, albumin-conjugated chemotherapeutic drugs or targeted therapies might be used to specifically target hypoxic cancers." (PMID 35177645, 2022). "Serum ALB levels are not only a window into the patient’s nutritional status but also a useful factor for predicting the prognosis of a patient with cancer which can be readily measured in resource-limited settings and will be critical for future clinical intervention studies in cancer patients." (PMID 36531036, 2022). "Albumin and BMI are commonly employed as markers of nutritional conditions, may be considered as inflammation parameters, and are related to age and cancer disease status." (PMID 35330404, 2022). "The nomogram incorporated routinely collected clinical data for dichotomous variables, including chronic respiratory disease, chronic kidney dysfunction, malignant tumor, abnormal neutrophil count, abnormal lymphocyte count, decreased serum albumin level, and increased HbA1c level." (PMID 36344933, 2022). "Also, proportion of ASA class, cancer stage, and lesion location was observed significantly in differences between two groups of patients with albumin < 35.0 g/L and albumin ≥ 35.0 g/L." (PMID 35773692, 2022). "The SARS-CoV-2 lockdown improved the nutritional status of cancer patients at admission, with a decrease in the percentage of weight loss and CRP concentrations together with an increase in albumin levels compared to oncological patients admitted the previous year in a single center." (PMID 35807934, 2022). "Ceruloplasmin could indirectly interact with cancer cells through a shared affinity with albumin for myeloperoxidase, followed by albumin binding FcRn receptors on cancer cells." (PMID 36546919, 2022). "Hence, the albumin nanoparticles developed herein present an excellent potential for delivering various drugs in cancer therapy." (PMID 34208533, 2021). "Serum albumin is also closely related to systemic inflammation in patients with cancer." (PMID 34836339, 2021). "In addition, albumin is preferentially internalized as the source of amino acids to cope with the enhanced cellular growth by the cancer cells expressing oncogenic Ras, whose activation is associated with cancer." (PMID 34298666, 2021). "This property can be utilized to deliver the cargo encapsulated in albumin to cancer cells." (PMID 34298666, 2021). "It is noteworthy that this study first conducted RCS analysis to analyze the nonlinear relationship between pre‐diagnostic serum albumin and cancer risk." (PMID 34041866, 2021). "This may be because AGR in patients with cancer reflects the balance of inflammatory protein and ALB." (PMID 34568033, 2021). "Similarly, high serum CRP and low serum albumin concentrations are prognostic markers for numerous cancers." (PMID 34962922, 2021).
cancer (continued). "Recently, albumin–globulin ratio (AGR), a serological indicator that reflects nutritional status and systemic inflammatory, has been reported to be associated with the prognosis of various cancers." (PMID 34568033, 2021). "It was reported that the prognostic nutritional index (PNI), calculated by combining serum albumin levels and the total circulating lymphocyte count, could reflect the nutritional and immunological status of patients having cancer." (PMID 34526045, 2021). "In addition, the cutoff values of H-CRP and albumin in the GPS were derived using prognosis data from cancer patients." (PMID 34270463, 2021). "A high ALI suggests low activity systemic inflammation in cancer patients, which may result from moderately increased BMI, increased albumin, and decreased NLR." (PMID 35096967, 2021). "Moreover, when patients who had an underlying cancer were excluded from the analysis, and CRP and albumin were combined in the measure of low-grade inflammation, GPS remained independently associated with higher 6-month mortality." (PMID 34962922, 2021). "In this context, albumin-based nanocarriers are being investigated in a variety of cancers." (PMID 34298666, 2021). "These albumin nanocomplexes exerted remarkable anticancer efficacy through the combined photothermal therapy and siRNA-mediated gene silencing, leading to around 80% of cancer cell death in vitro." (PMID 34869202, 2021). "Furthermore, serum albumin can be influenced by various diseases as well as cancer, such as heart, liver, and renal disease, and care is therefore needed in interpreting the meaning of serum albumin levels in clinical practice." (PMID 34473762, 2021). "Additionally, the CRP/albumin ratio, believed to be a predictor of overall survival in many cancers, was decreased during n-3 supplementation." (PMID 33801979, 2021). "In recent years, albumin–globulin ratio (AGR), a serological indicator that reflects nutritional status and systemic inflammatory, has been reported to be associated with the prognosis of various cancers." (PMID 34568033, 2021). "Additionally, about 35% of the patients had active cancer, and cachexic patients were likely to have low albumin levels." (PMID 34017041, 2021). "However, in the multivariable logistic regression analysis, variables associated with all-cause mortality were the presence of cancer, heart rate > 100 beats/min, BUN ≥ 30 mg/dL, albumin level ≤ 3.0 g/dL, and INR > 1.50." (PMID 34844565, 2021). "Low albumin was shown to be prognostic in many cancer types." (PMID 34884980, 2021). "In the univariate analysis, age (p < 0.0001), gender (p = 0.0074), BMI (p = 0.0103), serum albumin (p < 0.0001), total lymphocyte count (p < 0.0001), eGFR (p = 0.0026), CRP (p < 0.0001), and the presence of advanced cancer (p < 0.0001) were significant factors linked to SARC-F ≥4 points." (PMID 34575208, 2021). "Furthermore, the albumin-to-globulin ratio (AGR) has been widely recognized as a prognostic indicator of various cancers." (PMID 33732716, 2021). "In addition, inflammation inhibit albumin synthesis, and preoperative low serum ALB is significantly associated with reduced survival in patients with cancer." (PMID 34069272, 2021). "Indeed, there is now good evidence that CRP and albumin alone and these indices have prognostic value in adult cancer populations." (PMID 34944774, 2021). "The associations between albumin levels and cancer risks were not significant among females, while for males, inverse associations remained." (PMID 34041866, 2021). "The combination of CRP and albumin into a score, termed as the GPS, is a widely accepted index to characterize systemic inflammation and is associated with the prognosis in advanced cancer disease." (PMID 33763364, 2021). "Serum albumin, accounting for the majority (about 60%) of total plasma proteins, is one of the most direct laboratory indicators to reflect the nutritional status of cancer patients." (PMID 34475999, 2021).
cancer (continued). "Serum CRP and albumin levels are prognostic markers in multiple cancer types." (PMID 33434414, 2021). "Serum albumin is one of the most convenient and important indicators for assessing nutritional status, and previous reports have identified preAlb as an essential prognostic factor for several cancers, including NSCLC." (PMID 34473762, 2021). "Our results might be supportive to these studies, and it seems useful to investigate changes in serum albumin along with techniques for detection of micro cancer cells." (PMID 34473762, 2021). "Chemotherapy may also lead to weakened body functions in cancer patients, which will affect the ability of albumin synthesis." (PMID 34249995, 2021). "Both albumin and globulin could be involved in cancer progression in a variety of ways and play important roles." (PMID 33732716, 2021). "Local radiotherapy was performed on the metastatic lesions, and after radiotherapy, the patient received anti-PD-1 antibody (sintilimab 200 mg, q3w)combined with Albumin-bound (Nab)-paclitaxel (100 mg, qw) as the second-line therapy, but the patient's cancer was still observed to be progressing." (PMID 34109111, 2021). "Both ALB and ALP levels were significantly associated with the prognosis of cancer patients." (PMID 34539891, 2021). "In this review, we highlight the versatility of the serum albumin-based nanovehicles for different applications and briefly summarize the development and clinical potential of the serum albumin-based nanovehicles in cancer diagnosis and therapy." (PMID 34869202, 2021). "The C-reactive protein (CRP)/albumin (ALB) ratio serves as a prognostic marker for several cancers." (PMID 34154655, 2021). "However, when patients who had an underlying cancer were excluded from the analysis and CRP and albumin were combined in the measure of high-grade inflammation, poGPS remained significantly associated with higher 28-day mortality." (PMID 34962922, 2021). "A low level of albumin has been a useful prognostic tool for various cancers." (PMID 33496841, 2021). "In addition, albumin-based nanocarriers are finding their promising application in cancer immunotherapy in recent years." (PMID 34298666, 2021). "Therefore, the combination of carbon nanotubes with plasma albumin seems greatly promising in the delivery of cancer drugs to cancer cells." (PMID 34361101, 2021). "The prognostic value of CRP and albumin have been well established in a variety of cancers 15-18." (PMID 33758615, 2021). "We hypothesized that the readily available, routinely measured biomarkers CRP and albumin may have prognostic value in older cancer patients." (PMID 34944774, 2021). "Serum albumin levels decrease in chronic disease and in cancer as well." (PMID 33924581, 2021). "Thus far, serum albumin level, BMI, and NLR have been revealed to be significantly and independently associated with poorer survival outcomes in cancers, including OSCC." (PMID 34660250, 2021). "Previous studies have suggested that the inflammatory response in cancer patients is closely related to serum albumin levels and lymphocyte counts, and also suggest the systemic inflammatory response plays an important role in cancer development and progression." (PMID 33422067, 2021). "Besides, preoperative haemoglobin and serum albumin (ALB) levels are also reported as the prognostic predictors for long-term prognosis of cancers." (PMID 33676467, 2021). "Moreover, increasing interest has been drawn to using HSA-based NPs in cancer management after the FDA approval of paclitaxel-bound albumin NPs (AbraxaneTM)." (PMID 35056915, 2021). "This study develops a facile approach to co-deliver IR780 and GA with self-assembled albumin nanoparticles, which could relive hypoxia and suppress Hsp for clinical application of cancer phototherapy." (PMID 33407570, 2021).
cancer (continued). "In addition, it was also able to analyze diverse targets such as DNA hybridization, human serum albumin, bacteria, and cancer cells, and are considered valuable research technologies." (PMID 34821628, 2021). "Studies have demonstrated that preoperative low serum ALB levels may be considered as a marker of systemic inflammation and a poor prognostic indicator of survival outcome in cancer patients." (PMID 35127784, 2021). "Moreover, SPARC binds to albumin and co-localizes as a bound form in cancer tissues, and its expression is correlated with improved survival in several cancers." (PMID 34141613, 2021). "Summary of representative applications of serum albumin-based nanovehicles for cancer theranostics." (PMID 34869202, 2021). "Moreover, serum C‐reactive protein (CRP) and albumin are important inflammatory markers, and the C‐reactive protein:albumin ratio (CAR) is a prognostic factor in many cancers." (PMID 33434414, 2021). "Albumin has been reported as a biomarker of the nutritional status, and its level has been identified to be related to the co-morbidities and the prognosis for certain cancers." (PMID 33482792, 2021). "However, most of the studies involving aptamers conjugated to albumin nanocarriers are focused on the targeted delivery of chemotherapeutic drugs in cancer." (PMID 34298666, 2021). "Besides delivery of chemotherapeutic drugs, photosensitizers such as chlorin e6 and Indocyanine green have been encapsulated into albumin nanoparticles for PDT of cancer." (PMID 33407570, 2021). "One of the most promising carriers is albumin, which tends to accumulate near cancer cells." (PMID 34640229, 2021). "The low-PNI group showed significantly older age, lower BMI, lower lymphocyte count, lower albumin concentration, longer prothrombin time, lower total cholesterol concentration, higher C-reactive protein concentration, and higher concentration of cancer antigen 19–9." (PMID 34130648, 2021). "However, other potential factors were identified, such as the stage of cancer, corticosteroid intake, and nutritional status (nutritional markers: albumin, total protein, calcium, and bicarbonate levels)." (PMID 34444556, 2021). "The RCS model showed a significant linear association between serum albumin concentrations and overall cancer risk among the subjects (p‐overall < 0.0001, p‐nonlinear = 0.3716)." (PMID 34041866, 2021). "Albumin-globulin ratio (AGR), which is calculated as albumin / (total protein – albumin), is considered to be a strong prognostic tool for many cancers, as it combines the effectiveness of both albumin and globulin in predicting survival outcomes, particularly where solid tumors are involved." (PMID 33639645, 2021). "However, the long-lasting and far-reaching challenge for the treatment of cancers lies in how to construct the albumin nanometer drug delivery system with lead compounds and their derivatives." (PMID 34109887, 2021). "HCC cells from 5 to 6 patients and the primary hepatocytes were stained with CK-18, ALB, ARG-1 (biomarkers of hepatocyte and hepatocarcinoma cells) and AFP (biomarker of hepatocarcinoma cells), with cancer-associated fibroblasts (CAFs, from HCC sample) as the negative control." (PMID 34776939, 2021). "In addition, ALB is considered as an indicator of systemic inflammatory reaction in malignant tumors." (PMID 33789664, 2021). "Serum albumin concentration in the PNI reflects the nutritional status of patients with cancer." (PMID 34645392, 2021). "Serum albumin (sALB), a traditional serum biochemical marker synthesized by the liver, has been widely used to reflect the nutritional reserve of the host and considered as a prognostic indicator for malignant tumors." (PMID 34746006, 2021).
cancer (continued). "When patients with an underlying diagnosis of cancer were excluded from the analysis, combined biochemical markers of low-grade inflammation (GPS), serum CRP >10mg/L and low serum albumin concentrations <35 g/L remained independently associated with higher 6-month mortality." (PMID 34962922, 2021). "Studies have shown that systemic inflammatory markers, including cytokines, C-reactive protein (CRP), albumin, serum amyloid A and leukocytes, may be independent prognostic factors in cancer patients." (PMID 32022510, 2020). "The role of albumin as prognostic factor in patients with advanced cancer is known, although little indications that albumin levels could be a significant predictor in HPN patients have been reported." (PMID 32412178, 2020). "Moreover, increased CRP value is commonly evidenced in patients with cancer or infections, although decreasing albumin values occurs frequently during serious infections in otherwise healthy patients." (PMID 32344777, 2020). "If the carcinogenesis hypothesis is correct, calcium and albumin could be useful in cancer screening; if the genetic hypothesis is correct, they would not be (although their levels might define a population at increased risk)." (PMID 32723677, 2020). "Serum albumin is an important factor in assessing the nutritional status of patients and has been widely reported to be closely related to the prognosis of various cancers, including HCCA." (PMID 33505910, 2020). "Ras-transformed cancer cells are able to take up albumin through macropinocytosis." (PMID 33195279, 2020). "Therefore, blood components, such as WBCs, neutrophils, lymphocytes, monocytes, platelets and albumin, have been widely used for detecting the host inflammatory response in cancers." (PMID 32038986, 2020). "In the case of bis‐N,C‐chelated IrIII complexes (e.g. complex 12), we have shown that conjugation to the abundant serum protein albumin can have a dramatic effect on the transport of the photosensitizer into cancer cells, and specifically deliver the photosensitizer to the cell nucleus." (PMID 31310436, 2020). "Serum albumin was also reported to play a potentially important protective role in promoting the removal of reactive oxygen species, which is a process related to the pathogenesis of many diseases, including cancers." (PMID 33215031, 2020). "Both a decrease of protein intake or consuming nature of the cancer could lead to a decrease in albumin levels." (PMID 32087695, 2020). "Furthermore, albumin can bind to special receptors overexpressed on cancer cells and enhance nanoparticles binding and internalization." (PMID 35582218, 2020). "Albumin reflects nutritional status and systemic inflammatory response in cancer patients." (PMID 32232040, 2020). "It has long been recognized that albumin has prognostic value in patients with cancer." (PMID 32708140, 2020). "Cancer cells can produce cytokines that modulates the production of albumin." (PMID 33083290, 2020). "Serum albumin is also an independent prognostic indicator in several cancers." (PMID 33176752, 2020). "In theory, any cancer drug may be delivered IP but it is rational to explore IP delivery of albumin-bound chemotherapy." (PMID 31858848, 2020). "Therefore, the design of albumin-coupled cytotoxic drugs can be used for the presentation of anti-cancer active ingredients." (PMID 33542897, 2020). "Additionally, serum albumin, prealbumin, and fibrinogen are available in the medical records of most cancer patients, and measurements are inexpensive and reproducible." (PMID 31931816, 2020). "PNI is calculated using serum albumin level and peripheral total lymphocyte count; it was originally used to assess perioperative nutritional conditions and postoperative complications in patients with cancer." (PMID 32762748, 2020). "The Paclitaxel albumin-bound particles known as Abraxane® are used in cancer therapy." (PMID 33003636, 2020).